HMGA2 (high mobility group AT-hook 2)
Diseases named in the same sentence as HMGA2 in open-access papers (continued):
Sharing a sentence is not in itself a finding about the gene and the disease.
lipoblastoma (2 papers, 2014 to 2025). A lipoma usually occurring in the extremities of young children (usually boys). "Recently, an infantile lipoblastoma with rearrangements of the HMGA2 locus has been described as well." (PMID 24516594, 2014). "Lipoblastoma typically occurs in infants and children and often shows pleomorphic adenoma gene 1 (PLAG1) overexpression and PLAG1/HMGA2 rearrangements, with frequent cluster of differentiation 34 (CD34) and desmin expression." (PMID 41230282, 2025). "Lipoblastomas typically occur in infants and children, and even in older children and adult patients, positivity for PLAG1, CD34, and desmin, along with PLAG1 and HMGA2 rearrangements, aids in diagnosis." (PMID 41230282, 2025).
metabolic syndrome (2 papers, 2019 to 2021). A cluster of metabolic risk factors for CARDIOVASCULAR DISEASES and TYPE 2 DIABETES MELLITUS. "Our PheWAS findings revealed that PLCE1 and HMGA2 could be the genetic links between age-related cataract and metabolic syndrome." (PMID 34127677, 2021).
metastatic carcinoma (2 papers, 2016). A carcinoma which has spread from the original site of growth to another anatomic site. "High mobility group AT-hook 2 (HMGA2) is highly expressed in multiple metastatic carcinomas, in which it contributes to cancer progression, metastasis and poor prognosis by upregulating Snail expression and inducing epithelial mesenchymal transition (EMT)." (PMID 26818837, 2016). "HMGA2 induces EMT and invasiveness in epithelial tumors and high expression levels of the gene have been seen in primary as well as metastatic carcinomas." (PMID 27835588, 2016).
myeloid malignancies (2 papers, 2011 to 2020). "The loss of EZH2 in JAK2 V617F hematopoietic cells was shown to reduce H3K27me3 levels with an increase in H3K27 acetylation and the resulting activation of PRC2 target genes including High Mobility Group AT-Hook 2 (HMGA2), an oncogene previously implicated in PMF and other myeloid neoplasms." (PMID 32650416, 2020).
Nephropathy (2 papers, 2019 to 2021). A nonspecific term referring to disease or damage of the kidneys. "Common variation of HMGA2 gene can greatly enhance nephropathy of type 2 diabetic patients." (PMID 31885559, 2019).
neurofibroma (2 papers, 2019 to 2020). An intraneural or extraneural neoplasm arising from nerve tissues and neural sheaths. "Our analyses revealed that robust HMGA2 activation was more prevalent in human NF1-associated MPNSTs (13/16) than in sporadic MPNSTs (16/41), while HMGA2 was inactive in neurofibromas (0/7)." (PMID 31053152, 2019). "Immunohistochemistry (IHC) was used to detect HMGA2 expression in MPNST and neurofibroma patient samples." (PMID 31053152, 2019). "We analysed 6 neurofibroma samples, 8 NF1 MPNST samples and 8 sporadic MPNST samples by WB and found that HMGA2 protein levels were significantly higher in MPNST samples than in neurofibroma samples." (PMID 31053152, 2019). "NF1 MPNST samples exhibit higher HMGA2 positivity rates (13/16) than sporadic MPNST (16/41) and neurofibroma (0/7) patient samples." (PMID 31053152, 2019). "Moreover, using 64 paraffin-embedded tissues, we found that the rate of positive HMGA2 expression was significantly higher in NF1 MPNST samples (13/16) than in sporadic MPNST (16/41) and neurofibroma (0/7) samples." (PMID 31053152, 2019).
osteoarthritis (2 papers, 2023 to 2025). A noninflammatory degenerative joint disease occurring chiefly in older persons, characterized by degeneration of the articular cartilage, hypertrophy of bone at the margins and changes in the synovial membrane. "Notably, the identified here interactions between hsa-let7b/i, hsa-miR-221/222-3p, hsa-miR-302c, hsa-miR-181a, hsa-miR-331 with target genes HMGA2, IGF2BP3, STARD4, and APOL6 could prove to be the necessary tools that will convey iMSCs into the ideal mean for cell therapy in osteoarthritis." (PMID 37443790, 2023).
osteoporosis (2 papers, 2021). A condition of reduced bone mass, with decreased cortical thickness and a decrease in the number and size of the trabeculae of cancellous bone (but normal chemical composition), resulting in increased fracture incidence. "We identified HMGA2, which encodes high mobility group AT‐hook 2 protein and is part of multisubunit enhanceosome complexes, as a prime osteoporosis‐risk candidate." (PMID 33977200, 2021).
pancreatic (2 papers, 2020 to 2025). "Recently, the overexpression of several let-7 downstream targets including HMGA2, IGFBP1, and IGFBP3, were found to define a distinct patient group with poor prognosis in pancreatic cancer." (PMID 32651364, 2020).
polycystic ovary syndrome (2 papers, 2018 to 2024). A disorder that manifests as multiple cysts on the ovaries. "Most recently, as a candidate risk gene, HMGA2 was suggested to be related to polycystic ovary syndrome (PCOS)." (PMID 38473181, 2024).
prostate tumor (2 papers, 2015 to 2020). "Normal human epithelial prostate cell also exhibited low levels of HMGA2 expression in the plasma membrane which switched to predominantly cytoplasmic then nuclear localization with increasing prostate tumor grade, metastatic potential, and HMGA2 expression." (PMID 32365712, 2020).
retinal degeneration (2 papers, 2025). Degeneration of the retina. "Peripheral clusters, Cluster #15 (Oxidative Stress) and Cluster #16 (HMGA2 mRNA), provide insight into molecular and genetic mechanisms underlying retinal degeneration." (PMID 40428167, 2025).
thyroid nodule (2 papers, 2016 to 2022). A small circumscribed mass in the THYROID GLAND that can be of neoplastic growth or non-neoplastic abnormality. "In our study, HMGA2 was significantly upregulated in primary TC tissue, compared with benign and normal thyroid nodules." (PMID 27793213, 2016). "In the present study, we developed a panel that presents excellent performance in discriminating benign from malignant thyroid nodules by combining only four genes (FN1, GABRB2, NGEF and HMGA2)." (PMID 27793213, 2016).
tumors of the vulva (2 papers, 2015 to 2016). "We report a detailed study of 25 vulva tumors [22 SCC, 2 MM, 1 atypical squamous cell hyperplasia (AH)] analyzed for expression of the high-mobility group AT-hook family member genes HMGA2 and HMGA1, for mutations in the IDH1, IDH2 and TERT genes, and for methylation of the MGMT promoter." (PMID 25823555, 2015). "This is the first time that expression of the HMGA2 gene has been assessed in tumors of the vulva." (PMID 25823555, 2015). "The finding of 20 out of 24 malignant vulvar tumors, both SCC and MM, showing HMGA2 expression therefore was unexpected." (PMID 25823555, 2015). "Our results showed that HMGA2 and TERT may be of importance in the genesis and/or the progression of tumors of the vulva." (PMID 25823555, 2015).
Wilms tumor (2 papers, 2017 to 2024). An embryonal neoplasm characterized by the presence of epithelial, mesenchymal, and blastema components. "Also, rs968697 of the HMGA2 gene polymorphism in the promoter was significantly associated with CRC risk and Wilms tumor." (PMID 38802807, 2024).
ZIKV infection (2 papers, 2021 to 2023). "In mouse brain tissue and hNSCs (human neuronal stem cells), ZIKV infection upregulated miR-124-3p and let-7c, which downregulated transferrin receptor (TFRC) and HMGA2 (high-mobility group AT-hook 2) mRNAs, respectively." (PMID 37242305, 2023).
acute aortic dissection (1 paper, 2022). "One article reported a potential correlation between HMGA2 and EndMT in acute aortic dissection, but its function in EndMT was not validated by experiments." (PMID 35388172, 2022).
alopecia (1 paper, 2014). Hair loss usually from the scalp. "About 30% of HMGA2 transgenic mice also presented with severe alopecia associated with a maculopapular skin lesion." (PMID 25014774, 2014). "Skin lesions are not characteristic of human T-ALL, but about 30% of Eμ-HMGA2 transgenic mice developed severe alopecia with typical maculopapular skin lesions." (PMID 25014774, 2014).
amenorrhea (1 paper, 2019). The absence of menses in a woman who has achieved reproductive age. "TheTHADA rs13429458 and TOX3 rs4784165 variants were significantly associated with the combined oligo/amenorrhea (OA) and polycystic ovarian morphology subgroups while the HMGA2 rs2272046variant was significantly associated with the combined HA and OA subgroup." (PMID 31902981, 2019).
ampullary cancers (1 paper, 2023). "Our study aimed to interpret high-mobility group A protein 2 (HMGA2) expression in benign and precursor pancreatic lesions and pancreatic and ampullary carcinoma and to evaluate its relationship with epithelial–mesenchymal transition (EMT) and clinicopathological parameters." (PMID 37787719, 2023).
anaplastic astrocytoma (1 paper, 2016). "Recently, HMGA2 has been also reported to mediate the inhibitory effect of let-7 on cancer stem cells in anaplastic astrocytoma." (PMID 27486821, 2016).
angiolipoma (1 paper, 2009). A lipoma with prominent vascularity. "Thus, it seems as if also angiolipomas, at least to some extent, are associated with aberrant HMGA2 expression, but not on the basis of gross chromosomal rearrangements." (PMID 19508721, 2009).
angiomyxoma (1 paper, 2023). A benign soft tissue neoplasm characterized by the presence of neoplastic spindle and stellate cells, and vascular proliferation in a myxoid stroma. "RT-PCR studies have confirmed the presence of aberrant HMGA2 transcript expression in deep angiomyxomas exhibiting HMGA2 locus rearrangement." (PMID 37444513, 2023).
Azoospermia (1 paper, 2020). Absence of any measurable level of sperm,whereby spermatozoa cannot be observed even after centrifugation of the semen pellet. "Some target genes of the downregulated miRNAs, such as ACVR2A, CCND1, CCNE2, HMGA2, BMI1, NR2C2 and BCL2, have been associated with gonadal development, and germ cell maintenance through different pathways which could be relevant to the molecular mechanisms affected in KS patients with azoospermia." (PMID 32651451, 2020).
carcinoid tumours (1 paper, 2016). "It is worth noting that none of the 8 carcinoid tumours expressed HMGA2 protein." (PMID 26858029, 2016).
carcinoma ex pleomorphic adenoma (1 paper, 2023). A carcinoma arising in a pre-existing pleomorphic adenoma. "PA and carcinoma ex-pleomorphic adenoma (CAexPA) are characterized by translocations associated to the high-mobility group AT-hook 2 (HMGA2), gene which are frequent (~96%) on PAs and less common in PA and CAexPA (~30%)." (PMID 37373187, 2023).
cerebral infarction (1 paper, 2022). An ischemic condition of the brain, producing a persistent focal neurological deficit in the area of distribution of the cerebral arteries. "This study is aimed at evaluating the effects of HMGA2 on cerebral infarction-induced brain tissue damage and its underlying mechanisms." (PMID 35966335, 2022). "These research are consistent with our findings, which showed that downregulation of HMGA2 alleviated the damage associated with cerebral infarction-induced inflammatory response and brain cellular apoptosis." (PMID 35966335, 2022). "HMGA2 might be able to alleviate the damage associated with cerebral infarction-induced inflammatory response and cell apoptosis." (PMID 35966335, 2022). "Therefore, this study explored the effect of HMGA2 on cerebral infarction-induced brain tissue damage and its underlying mechanisms." (PMID 35966335, 2022). "After cerebral infarction, the rats were transfected with two different lentiviruses carrying sh-NC and sh-HMGA2." (PMID 35966335, 2022). "Transfection with sh-HMGA2 resulted in obviously suppressed brain water content in the cerebral infarction condition." (PMID 35966335, 2022). "Together, these results demonstrated that inhibition of HMGA2 ameliorated the neuron function and brain injury in cerebral infarction rats." (PMID 35966335, 2022). "In contrast, sh-HMGA2 treatment reduced the brain infarction induced neuronal morphology changes and ameliorated the interstitial edema." (PMID 35966335, 2022). "Using this model, this study first demonstrated that inhibition of HMGA2 exerted a neuroprotective effect on cerebral infarction, by reducing the brain infarct areas and protecting the brain from infarction-induced neuronal morphology changes and interstitial edema." (PMID 35966335, 2022). "Moreover, downregulation of HMGA2 had a protective effect on the brain damage derived from cerebral infarction by mediating the TLR4/NF-κB pathway." (PMID 35966335, 2022). "However, there are few studies on the expression and function of HMGA2 in cerebral infarction as well as its related mechanisms." (PMID 35966335, 2022). "Adult Sprague Dawley rats were pretreated with sh-HMGA2 before cerebral infarction operation." (PMID 35966335, 2022). "Densitometric analysis of the bands from the western blots shown an increased HMGA2 level after cerebral infarction and a decrease in HMGA2 expression in the MCAO + sh-HMGA2 group." (PMID 35966335, 2022). "The results indicated that the expression levels of TLR4, p65, p-p65, and p-IκB in cerebral infarction rats were significantly increased compared with the control group, which were remarkably attenuated in the MCAO + sh-HMGA2 group." (PMID 35966335, 2022).
cervical (1 paper, 2018). "SiHa, CaSki, and S12 cell lines were used to explore the role of HMGA2 in cervical carcinogenesis." (PMID 29487700, 2018).
cervical tumors (1 paper, 2021). "ZNF382 was firstly identified as a direct repressor for several oncogenes (i.e., MYC, MITF, HMGA2, and CDK6) across distinct types of cancers, including lung, esophageal, colon, stomach, breast, and cervical tumors." (PMID 34638319, 2021).
cholangiocarcinoma (1 paper, 2021). A carcinoma that arises from the intrahepatic biliary tree (intrahepatic cholangiocarcinoma) or from the junction, or adjacent to the junction, of the right and left hepatic ducts (hilar cholangiocarcinoma). "In conclusion, the results of the present study suggest that the cholangiocarcinoma (CHOL)-hub genes (SNX15, ATP2A1, PDCD10, BET1, and HMGA2) can be used as biomarkers of tumor progression, metastasis, therapy outcome, and poor prognoses of CHOL." (PMID 34831096, 2021).
chondromatous tumors (1 paper, 2015). "It should be emphasized that the role of HMGA2 in chondromatous tumors is still studied only very rudimentary in-as-much as only six soft tissue chondromas, two skeletal chondromas, and three periosteal chondromas have been subjected to this type of analysis." (PMID 26043835, 2015).
chronic cholecystitis (1 paper, 2012). "HMGA2 expression of gallbladder adenocarcinoma was significantly higher than that of adjacent tissue, polyps and chronic cholecystitis gallbladder epithelium (P <0.01), but CD9 expression was the opposite (P <0.05 or P <0.01)." (PMID 22613496, 2012). "Our data show that the HMGA2 positive expression ratio of gallbladder adenocarcinoma was significantly higher than that of the adjacent tissues, adenomatous polyps and gallbladder epithelium of chronic cholecystitis." (PMID 22613496, 2012). "The resected specimens of 108 cases of gallbladder adenocarcinoma, 46 cases of adjacent tissue, 15 cases of polyps and 35 cases of chronic cholecystitis were made into conventional paraffin-embedded sections, using the method of EnVision immunohistochemistry to stain HMGA2 and CD9." (PMID 22613496, 2012). "HMGA2 expression of gallbladder adenocarcinoma was significantly higher than that of adenocarcinoma adjacent tissues (= 16.13, P <0.01), polyps (= 8.19, P <0.01) and chronic cholecystitis (= 21.41, P <0.01); but CD9 expression was the opposite (P <0.05 or P <0.01)." (PMID 22613496, 2012).
congenital heart disease (1 paper, 2024). A heart disease that is present at birth. "MINK1 contributes to the development of congenital heart disease and takes part in heart development, regulating Spemann organizer cell fate possibly via its role in the inhibition of canonical Wnt signaling and through HMGA2 protein." (PMID 39727954, 2024).
COVID-19 (1 paper, 2022). A disease caused by infection with severe acute respiratory syndrome coronavirus 2. "To conclude, DNMT1, HMGA1, and HMGA2 might be central TFs in the TF–gene regulatory network in COVID-19/NSCLC." (PMID 35721149, 2022).
dissection (1 paper, 2022). The separation and isolation of tissues for surgical purposes, or for the analysis or study of their structures. "HMGA2 has been widely investigated in aortic dissection, and has been found to regulate rat aortic vascular SMCs viability and apoptosis." (PMID 35212609, 2022).
ductal adenocarcinoma (1 paper, 2023). "In the present study, we examined the expression of HMGA2 protein in the normal-appearing pancreas, low- and high-grade PanIN, and ductal adenocarcinoma." (PMID 37787719, 2023).
esophageal tumor (1 paper, 2016). "Together these results suggest that HMGA1 and HMGA2 proteins are differentially expressed, according to the esophageal tumor histopathological subtype." (PMID 27027341, 2016). "In this way, the antagonist HMGA1 and HMGA2 expression pattern observed in esophageal tumors (ESCC and EAC) could result from the activation of specific embrionary-like mechanisms during the distinct development of esophageal squamous cell and adenocarcinoma." (PMID 27027341, 2016). "Next, since ESCC and EAC represent the two main esophageal tumors histotypes, we investigated whether HMGA1 and HMGA2 expression could differ, according to the histological origin of the esophageal tumors." (PMID 27027341, 2016).
fibrosis (1 paper, 2017). the formation of excess fibrous connective tissue in an organ or tissue in a reparative or reactive process. "Several target genes of miR-26a and -26b have been identified for fibrosis thus far,including collagen I, CTGF, Smad4 and HMGA2.28,29, 30 Inthe current study, we uncovered a novel target gene Jagged-1 for miR-26a and -26b." (PMID 28622289, 2017).
fumarate hydratase deficiency (1 paper, 2024). "With regards to pathophysiology, research has identified MED12 mutations, HMGA2 overexpression, fumarate hydratase deficiency, and cytogenetic abnormalities as contributors to the development of UL." (PMID 38790186, 2024).
gallbladder adenocarcinoma (1 paper, 2012). A carcinoma that arises from glandular epithelial cells of the gall bladder. "The data also suggest the prognostic significance of HMGA2 and/or CD9 expression as a tumor biological marker in patients with gallbladder adenocarcinoma." (PMID 22613496, 2012). "The expression of HMGA2 and/or CD9 might be closely related to the carcinogenesis, clinical biological behaviors and prognosis of gallbladder adenocarcinoma." (PMID 22613496, 2012). "In the present study, our data showed that the expression of HMGA2 and/or CD9 might be closely related to carcinogenesis, clinical biological behaviors, and prognosis of gallbladder adenocarcinoma." (PMID 22613496, 2012).
gastric tumor (1 paper, 2024). "HMGA2 stimulates Wnt/β-catenin signaling is activated by HMGA2 to mediate EMT and promote the progression of gastric tumor cells." (PMID 38733529, 2024).
gestational diabetes (1 paper, 2022). Carbohydrate intolerance first diagnosed during pregnancy. "Unfortunately, there are scarce publications on linking HMGA2, CRTC2 and SLC6A15 genes to gestational diabetes, so further research on this topic needs to be carried out to enable the comparison of our findings presented in this study with other data." (PMID 35454338, 2022).